GATA1 (GATA binding protein 1)
Diseases named in the same sentence as GATA1 in open-access papers (continued):
Sharing a sentence is not in itself a finding about the gene and the disease.
thyroid cancer (3 papers, 2019 to 2024). "The receptor TNFRSF10B could cause degradation via ubiquitination and trigger the transcription factor GATA1, and its mutation can enhance the suppression of apoptosis in thyroid cancer cells to promote the selective growth of cancer cells." (PMID 31126066, 2019). "MGP expression was positively closely related to GATA1 in bladder, breast, colorectal, esophageal, head and neck, kidney, liver, lung, prostate, and thyroid cancers." (PMID 39684309, 2024).
triple-negative breast carcinoma (3 papers, 2021 to 2024). An invasive breast carcinoma which is negative for expression of estrogen receptor (ER), progesterone receptor (PR), and human epidermal growth factor receptor 2 (HER2). "Another study reported that GATA1 deSUMOylation at K137 promoted its binding to CSN5 promoter and caused transcriptional activation of CSN5 in triple-negative breast cancer." (PMID 39277582, 2024). "GATA1 has been identified as a key transcription factor participating in the Triple-Negative Breast Cancer by regulating the expression of lncRNA HNF1A-AS1." (PMID 34425872, 2021).
acute basophilic leukemia (2 papers, 2022 to 2024). A rare acute myeloid leukemia in which the immature cells differentiate towards basophils. "A recurrent translocation was also detected in rare cases of acute basophilic leukemia in which MYB was fused to the GATA1 gene, causing the expression of a MYB-GATA1 fusion protein." (PMID 38542205, 2024). "MYB may play a key role in the leukemic transformation process, similar to MYB::GATA1 rearrangements in acute basophilic leukemia." (PMID 36077669, 2022).
anaphylaxis (2 papers, 2019 to 2022). An acute hypersensitivity reaction that occurs from exposure to an allergen. "While the role of GATA1 in anaphylaxis has only been linked to mast cell activation, reduced GATA1 activity in anaphylaxis patients may drive reaction severity through downstream effects on platelets and other cell types." (PMID 36583159, 2022). "Given the reduced mast cell differentiation efficiency in ΔdblGata mice, we examined the requirement for GATA-1 signaling in IgE-mediated anaphylaxis." (PMID 31369572, 2019). "Herein, we examine the requirement of GATA-1 signaling in mast cell effector function and IgE-mast cell-dependent anaphylaxis." (PMID 31369572, 2019). "Our validation work demonstrated the downregulation of six platelet‐related genes (TLN1, GATA1, SELP, SPARC, MPL and F13A1) in anaphylaxis patients compared with healthy controls." (PMID 36583159, 2022). "Six genes (GATA1 (P‐value = 2.52 × 10−2), SELP (P‐value = 1.86 × 10−2), MPL (P‐value = 2.72 × 10−2), F13A1 (P‐value = 1.62 × 10−2), SPARC (P‐value = 2.97 × 10−2) and TLN1 (P‐value = 6.13 × 10−3)) were significantly downregulated in anaphylaxis patients compared with healthy controls." (PMID 36583159, 2022). "Seven genes (TLN1, GATA1, SELP, GP1BA, MPL, F13A1 and SPARC) were also downregulated in patients with severe anaphylaxis who did not receive adrenaline before ED arrival, compared with healthy controls." (PMID 36583159, 2022).
bladder cancer (2 papers, 2012 to 2025). "Beyond HNSCC, GATA1 has been implicated in breast and bladder cancers, suggesting its role may extend to other solid tumors." (PMID 40259045, 2025).
cervical cancer (2 papers, 2013 to 2023). A primary or metastatic malignant neoplasm involving the cervix. "For example, in alveolar epithelial cells, such as erythroid cells, transcription of the HBB gene is regulated by GATA-1, but this is not the case in cervical cancer." (PMID 37239002, 2023). "However, the expression of transcription factors for erythropoiesis, including GATA-1, KLF1, and SCL/TAL1, was not changed significantly in cervical cancer tissues compared to the controls (data not shown)." (PMID 23349856, 2013).
chronic myeloproliferative neoplasm (2 papers, 2021 to 2023). "Micromegakaryocytes in chronic myeloproliferative neoplasms (MPN) are GATA1 negative and produce much higher amount of TGF-β1." (PMID 37814319, 2023).
clear cell renal cell carcinoma (2 papers, 2022 to 2024). "By reviewing literature, we have discovered that the low GATA1 expression is associated with poor prognosis of clear renal cell carcinoma and recurrence of lymph node metastasis." (PMID 36210802, 2022). "On the other hand, it was shown that decreased mRNA expression of GATA1 was associated with tumor aggressiveness and poor outcome in clear cell renal cell carcinoma (ccRCC), implying that GATA1 may be associated with the progression and aggressiveness of ccRCC." (PMID 39684309, 2024).
colitis (2 papers, 2022 to 2025). Inflammation of the colon. "We propose the hypothesis that vitamin D may ameliorate the DSS-induced colitis by suppressing the HIF-1α/GATA1/STING signaling pathway." (PMID 40563965, 2025). "In this study we aimed to investigate how the epigenetic regulation of DNA demethylation of the p2x7r locus guided by the transcription factor GATA binding protein 1 (GATA1) in spinal astrocytes affects chronic visceral pain in adult rats with neonatal colonic inflammation (NCI)." (PMID 34890016, 2022). "Immunohistochemical staining found that vitamin D intervention reduced the expression of GATA-1, suggesting that vitamin D may inhibit the activation of the STING pathway through GATA-1 and improve DSS-induced colitis." (PMID 40563965, 2025).
cryptorchidism (2 papers, 2015 to 2023). The failure of one or both testes of a male fetus to descend from the abdomen into the scrotum during the late part of pregnancy. "It has been shown that mutation of GATA1 causes human cryptorchidism and its expression in Sertoli cells is conserved between human and mouse." (PMID 37096870, 2023). "Mutation in the GATA1 has been reported in cryptorchidism, implicating GATA1 deficiency is associated male reproductive disorder." (PMID 25880873, 2015).
dengue (2 papers, 2022 to 2023). "Based on these reports we framed the hypothesis that EDRF1, GATA1, and spectrins might be affected during the dengue virus infection." (PMID 37534186, 2023). "Thus, due to the importance of the GATA1 gene in thrombopoiesis and in dengue severity, this study needs to be further validated in a large number of populations residing in different geographical regions." (PMID 35771876, 2022).
eosinophilia (2 papers, 2021 to 2023). "The eosinophils-deficient IL-5 gene-deficient mice and GATA1 gene-deficient mice, both develop tissue eosinophilia following disease induction in experimental models." (PMID 37524769, 2023).
essential thrombocythaemia (2 papers, 2021 to 2023). "Accordingly, GATA1 is weakly expressed in CML but elevated in essential thrombocythemia and polycythemia vera—all myeloproliferative neoplasias." (PMID 38203204, 2023). "Double staining showed the CAL2‐positive megakaryocytes in essential thrombocythaemia patient to co‐express GATA‐1." (PMID 32929772, 2021).
food allergies (2 papers, 2019 to 2021). "To determine the contribution of GATA-1 signaling in MC-dependent inflammatory responses, we employed an active food allergy model." (PMID 31369572, 2019). "Sribava found that the ILC2 content in the small intestine was increased in mice with IgE-mediated food allergies, and the content of ILC2s was decreased in the small intestine after GATA-1 activity was reduced, indicating the roles of ILC2s and GATA-1 in IgE-mediated food allergies." (PMID 34177881, 2021).
gastric cancer (2 papers, 2012 to 2022). A primary or metastatic malignant neoplasm involving the stomach. "The interaction of the transcription factors RELA, IRF1, ESR1, AR, POU5F1, TRIM28, and GATA1 with LOC441461 affected the degree of the malignancy of gastric cancer by modulating gene transcription." (PMID 35267457, 2022). "Overall, we suggest that LOC441461 modulates gene transcription, inducing the malignancy of gastric cancer by interacting with RELA, IRF1, ESR1, AR, POU5F1, TRIM28, and GATA1." (PMID 35267457, 2022).
glioblastoma (2 papers, 2020 to 2024). The most malignant astrocytic tumor (WHO grade IV). "In glioblastomas, it was demonstrated that the interaction of GATA1 and MMP-2 enhanced glioblastoma invasion and migration." (PMID 39684309, 2024). "Several of these TFs, including GATA1 and SP1, have been suggested to be involved in the progression and invasiveness of glioblastoma cells." (PMID 32974985, 2020).
Intellectual disability (2 papers, 2022 to 2023). "A number of transcription factors, including FOXC2 and GATA1, play a role in neuronal dysfunction and intellectual disability, which are affected by impaired protein synthesis and splicing." (PMID 37359008, 2023). "Impairments in protein synthesis and splicing mediated in part by transcription factors such as FOXC2, GATA1, contribute to impaired neuronal function and concurrence of intellectual disability and craniofacial anomalies in our patients." (PMID 35436926, 2022).
lymphoma (2 papers, 2022 to 2025). A malignant (clonal) proliferation of B- lymphocytes or T- lymphocytes which involves the lymph nodes, bone marrow and/or extranodal sites. "In addition, the relationship between GATA1 expression and survival was analyzed using lymphoma-related data from TCGA." (PMID 40391074, 2025).
neuroblastoma (2 papers, 2018 to 2022). Neuroblastoma (NB) is the most common solid, extracranial childhood tumor. "Further, overexpression of WDR13 in IMR-32 human neuroblastoma cell line decreased the transcript levels of Gata1 by 1.5-fold (Mann–Whitney; p < 0.05)." (PMID 29743870, 2018).
osteogenic sarcoma (2 papers, 2009 to 2019). "We found that HIF1A and HMGN5 were upregulated in osteosarcoma (OS) cells cultured in the hypoxic environment, and the results of overexpression and knockdown experiments showed that HIF1A upregulated the transcription factor GATA1 and further promoted the expression of HMGN5." (PMID 31930127, 2019). "When the same experiment was performed with the human osteogenic sarcoma SAOS-2 cell line, which does not express endogenous GATA-1 or pRb, neither retrovirally expressed hGATA-1 nor hGATA-1Rb− had an effect on cell proliferation." (PMID 19513100, 2009).
osteoporosis (2 papers, 2024). A condition of reduced bone mass, with decreased cortical thickness and a decrease in the number and size of the trabeculae of cancellous bone (but normal chemical composition), resulting in increased fracture incidence. "However, detailed reports on the association between osteoporosis and the GATA1 gene with bone marrow fibrosis have yet to be found." (PMID 38967699, 2024).
pancreatic ductal adenocarcinoma (2 papers, 2019 to 2024). An infiltrating adenocarcinoma that arises from the epithelial cells of the pancreas. "In pancreatic ductal adenocarcinoma tissues, GATA1 was found to be highly expressed and an independent predictor of prognosis and response to gemcitabine therapy through the anti-apoptotic pathway." (PMID 39684309, 2024). "GATA1 is highly expressed in pancreatic ductal adenocarcinoma (PDAC) tissues, and GATA1 status is an independent predictor of prognosis and response to gemcitabine therapy." (PMID 31093285, 2019).
porphyria (2 papers, 2018 to 2021). Porphyria is a group of diseases in which substances called porphyrins build up, negatively affecting the skin or nervous system. "The other three forms of porphyria (ADP, CEP, and EPP) are autosomal recessive conditions, although X-linked inheritance is also reported in the cases carrying GATA1 and ALAS2 mutations, which are responsible for CEP and XLP, respectively." (PMID 34441276, 2021). "The roles of ALAS2, GATA1, and CLPX genes in the pathogenesis of porphyria have been identified." (PMID 34441276, 2021).
Sepsis (2 papers, 2023 to 2025). Sepsis is defined as life-threatening organ dysfunction caused by a dysregulated host response to infection. "GATA1 dysregulation also increases the susceptibility to infections and sepsis." (PMID 40650665, 2025).
Thrombocytosis (2 papers, 2022 to 2025). Increased numbers of platelets in the peripheral blood. "GATA1 also plays a critical role in inflammation‐associated thrombocytosis." (PMID 35644988, 2022).
ascariasis (1 paper, 2021). An infection that is caused by the roundworm Ascaris lumbricoides, many cases of which remain asymptomatic. "To further investigate the role of eosinophils in SIgA production during larval ascariasis, we evaluated the immune response to Ascaris infection in non-eosinophilic mice (GATA1-/-) and compared it to that of wild-type mice (WT BALB/c)." (PMID 34784389, 2021).
autoimmune disease (1 paper, 2022). A disorder resulting from loss of function or tissue destruction of an organ or multiple organs, arising from humoral or cellular immune responses of the individual to their own tissue constituents. "GATA1 reportedly regulates the basal transcription of mSTING genes and plays a key role in the pathogenesis of autoimmune diseases and cancer." (PMID 35969172, 2022).
Bernard-Soulier syndrome (1 paper, 2013). Bernard Soulier syndrome (BSS) is an inherited platelet disorder characterized by mild to severe bleeding tendency, macrothrombocytopenia and absent ristocetin-induced platelet agglutination. "In keeping with this concept, a point mutation in a GATA-binding site in the GP1BB promoter proximal region causes a form of Bernard-Soulier syndrome 60, illustrating the link between GATA1 and expression of a typical marker of mature MKs." (PMID 23311859, 2013).
bone marrow failure syndrome (1 paper, 2024). "Given the frequency of BM failure within the pedigree, we examined known recurrent mutations of inherited bone marrow failure syndromes, such as mutations in genes encoding ribosomal proteins (RP), ALAS2, GATA1, CDAN1, EPO, EPOR, etc.." (PMID 38971858, 2024).
cardiac hypertrophy (1 paper, 2023). "Additionally, we observed a trend of mild spontaneous cardiac hypertrophy and fibrosis in Gata1 KO mice in terms of E/e', HW/TL and Sirius Red staining." (PMID 37773694, 2023).
cardiomyopathy (1 paper, 2021). A disease of the heart muscle or myocardium proper. "GATA5 and GATA1 are closely related to cardiomyopathy diseases such as dilated cardiomyopathy, although their role in HCM has not yet been reported." (PMID 34054926, 2021).
congenital myopathy (1 paper, 2020). "Red blood cell (RBC) thalassemic-like abnormalities are typically found in GATA1-related thrombocytopenia (GATA1-RT), while Stormorken- and York platelet syndrome share the finding of congenital myopathy." (PMID 32079152, 2020).
endometrial tumor (1 paper, 2022). "By comparing the GATA1 gene expression between the patients’ endometrial tumor tissue and normal tissues, we found that the GATA1 expression was higher in the normal tissue than the tumor tissue." (PMID 36210802, 2022).
eosinophilic leukemia (1 paper, 2021). "Finally, blockade of eosinophilic leukemia maturation by ablating Gata1 or Xbp1 prevents relapse in a significant proportion of mice." (PMID 34764270, 2021).
epilepsy (1 paper, 2025). A brain disorder characterized by episodes of abnormally increased neuronal discharge resulting in transient episodes of sensory or motor neurological dysfunction, or psychic dysfunction. "Case No. 12, a girl who had a heterozygous VUS GATA1 variant, also had epilepsy." (PMID 40941697, 2025).
factor VII deficiency (1 paper, 2021). A coagulation disorder characterized by the partial or complete absence of factor VII activity in the blood. "We collected data on: hemostatic genes (factor V deficiency, von Willebrand’s disease, factor VII deficiency), protrombothic genes (factor V Leiden, MTHFR mutation, protein C deficiency), collagen genes (COL4A1 and COL4A2 mutations), and X linked GATA1 gene mutation." (PMID 33920939, 2021).
Gaucher disease (1 paper, 2013). Gaucher disease (GD) is a lysosomal storage disorder encompassing three main forms (types 1, 2 and 3), a fetal form and a variant with cardiac involvement (Gaucher disease - ophthalmoplegia - cardiovascular calcification or Gaucher-like disease). "The fundamental cellular/molecular mechanisms of this reciprocal expression of Pu.1/Gata1 and their roles in the pathophysiology of Gaucher disease are the subject of further study." (PMID 24124461, 2013). "The decreased erythropoietic gene expression and increased myelopoietic gene expression indicates a reciprocal interaction of Pu.1/Gata1 expression and regulation in the spleen of Gaucher disease." (PMID 24124461, 2013).
hepatoblastoma (1 paper, 2022). Hepatoblastoma (HB) is a malignant hepatic tumor and is the most common pediatric liver cancer. "We identified high levels of IGF2 in patients enriched for Hepatoblastoma I and Hepatoblastoma II signatures, GATA1 in patients enriched for the Erythroid-like signature, POSTN in patients enriched for the DCN-high signature, and CHGA in patient 8 who was enriched in the Neuroendocrine signature." (PMID 36008377, 2022).
hyperandrogenism (1 paper, 2022). Excessive secretion of androgens from the adrenal glands or gonads. "Interestingly, our previous research revealed that baicalin would potentially be an effective therapeutic agent for hyperandrogenism in PCOS by inhibiting the recruitment of GATA1 to the HSD3B2 promoter in ovarian tissue." (PMID 35600955, 2022).
iron deficiency (1 paper, 2023). "To evaluate the effect of iron deficiency on cell proliferation of germ cells, primary spermatocyte and Sertoli cells in testis and epididymis, we tested the co-staining of DDX4+/Ki67+, SCP3+/Ki67+ GATA1+/Ki67+ and GATA1+/BrdU+." (PMID 37346174, 2023). "Iron deficiency not only decreases electron transport, oxidative phosphorylation level, and ATP production but also suppresses the activity of ribonucleotide reductase and the expression of Ki67, DDX4, GATA1, and SCP3, indicating that Sev affects the spermatogenesis and development." (PMID 37346174, 2023).
kidney cancer (1 paper, 2024). Primary or metastatic malignant neoplasm involving the kidney. "GATA1 expression was significantly higher in noncancerous tissue than in kidney cancer." (PMID 39684309, 2024).
medulloblastoma (1 paper, 2011). A malignant, invasive embryonal neoplasm arising from the cerebellum. "The specific bi-modal distribution of OTX2 binding around the TSSs, as we investigated in medulloblastoma, strongly differs from the binding patterns of MYC and other transcription factors like GATA1 and TCF4." (PMID 22016811, 2011).
Miscarriage (1 paper, 2026). A pregnancy that ends at a stage in which the fetus is incapable of surviving on its own, defined as the spontaneous loss of a fetus before the 22th week of pregnancy. "In this study, based on two UM case-control groups, four ZnCl2-exposed mouse models, and a ZnCl2-exposed trophoblast Swan 71 cell model, we obtain a consistent conclusion that excessive Zn exposure causes disulfidptosis and thus induces miscarriage by up-regulating the GATA1/METTL1/SLC7A11 axis." (PMID 42095470, 2026). "Knockdown of murine Slc7a11, Gata1, or Mettl1, or supplement with NADPH suppresses mouse placental disulfidptosis and alleviates mouse miscarriage." (PMID 42095470, 2026).
Monge’s disease (1 paper, 2023). "Our previous studies have shown a critical role for GATA1 in regulating the excessive erythropoiesis in Monge’s disease." (PMID 37022795, 2023). "Indeed, we detected decreased expression of EPOR (a downstream target of HIF-1) following CSNK2B KD, suggesting that, in addition to GATA1, HIF signaling might be another potential mechanism underlying the role of CSNK2B in excessive erythropoiesis in Monge’s disease." (PMID 37022795, 2023).